RNU1-51P (RNA, U1 small nuclear 51, pseudogene)
Gene: Small nuclear RNA gene on chromosome 4 (189,709,539 to 189,709,714, reverse strand). Ensembl gene ENSG00000202215.
Homologues: Orthologues: chimpanzee U1 (98% identical), macaque U1 (91% identical), pig U1 (66% identical), rat U1 (61% identical), guinea pig U1 (60% identical), mouse Gm25115 (52% identical). Paralogues in human: U1 (98% identical), RNU1-1 (74% identical), RNU1-2 (74% identical), RNU1-27P (74% identical), RNU1-28P (74% identical), RNU1-3 (74% identical), RNU1-4 (74% identical), RNU1-89P (74% identical), RNVU1-18 (74% identical), RNVU1-29 (74% identical), U1 (74% identical), RNU1-18P (74% identical), and 133 more.